IL31 (interleukin 31)
Diseases named in the same sentence as IL31 in open-access papers (continued):
Sharing a sentence is not in itself a finding about the gene and the disease.
osteoporosis (10 papers, 2015 to 2025). A condition of reduced bone mass, with decreased cortical thickness and a decrease in the number and size of the trabeculae of cancellous bone (but normal chemical composition), resulting in increased fracture incidence. "On the other hand, IL-33 has been shown to enhance bone formation and prevent bone loss by modulating the expression of IL31, suggesting that it has a protective effect against osteoporosis in animal studies." (PMID 39767728, 2024). "Interleukin-33 (IL-33) and interleukin-31 (IL-31) are two cytokines that have been implicated in the pathogenesis of several bone-related disorders, including osteoporosis." (PMID 39767728, 2024). "Notably, higher levels of IL-31 were associated with increased age, suggesting an association between Th2 cytokine overexpression and bone resorption in senile osteoporosis." (PMID 33644103, 2021). "The deepening of the knowledge of the roles of IL-31 and IL-33 in the immunoskeletal interface can contribute to better understanding of those mechanisms underlying the functioning of the immune system that trigger osteoclastogenic inflammatory reactions, crucial in osteoporosis." (PMID 32069819, 2020). "It appears from clinical and experimental data that the IL-33/IL-31 axis plays a significant part in osteoporosis." (PMID 39224568, 2024). "Numerous inflammatory cytokines have been demonstrated to be involved in bone remodeling, and there are both in vitro and clinical observations which suggest a role for IL-31 in the development of osteoporosis." (PMID 33644103, 2021). "In a study in postmenopausal females, patients with osteoporosis exhibited elevated levels of serum IL-31 compared with healthy controls (p < 0.049)." (PMID 33644103, 2021). "Among these a significative role is played by IL-31 and IL-33, whose role has recently been investigated also in osteoporosis." (PMID 31973226, 2020). "Many of the transcription factors and cytokines pathogenetically involved in the development of osteoporosis are regulated by IL-31." (PMID 32069819, 2020). "Recent evidence suggests that the IL-33/IL-31 axis constitutes a link between accelerated atherosclerosis and osteoporosis in psoriatic arthritis (PsA)." (PMID 32069819, 2020). "Clinical and experimental observations suggest an important role of the IL-33/IL-31 axis in osteoporosis." (PMID 32069819, 2020). "Recently evidence has emerged of the role of two new cytokines of the Th2 profile, IL-31 and IL-33, in bone remodeling and osteoporosis." (PMID 32069819, 2020). "The increased IL-31 production by senescent inflammatory cells contributes to senile osteoporosis development." (PMID 32069819, 2020). "IL-31 influences Th1/Th17 osteoclastogenetic inflammation and limits Th2 osteoprotective processes, thus favoring osteoporosis." (PMID 32069819, 2020). "In general, it can therefore be suggested that IL-31 is osteoclastogenic, while IL-33 is protective, in the context of osteoporosis." (PMID 32069819, 2020). "Here we focus on two newly discovered Th2 cytokines, IL-31 and IL-33, whose implications in osteoporosis are recently emerging." (PMID 32069819, 2020). "Overall, our studies have shown that IL-33 is decreased in osteoporosis, whereas IL-31 is increased." (PMID 32069819, 2020). "A malfunction of these IL-31 shared signaling pathways is involved in several diseases in addition to osteoporosis, including diabetes, cancer, neurological and cardiovascular diseases, all in some way also related to impaired bone remodeling and osteoporosis." (PMID 32069819, 2020). "In fact, elderly subjects with osteoporosis have higher IL-31 serum levels than healthy young and old control subjects." (PMID 32069819, 2020). "Several transcription factors and cytokines play a role in the development of osteoporosis and IL-31 is involved in their regulation." (PMID 31973226, 2020).
osteoporosis (continued). "A clear understanding of IL-31 involvement in bone resorption immunopathology can provide more effective strategies for the treatment of senile osteoporosis." (PMID 31798591, 2019). "Measurements of the serum of IL-31 and IL-33 were performed both in women with osteoporosis and healthy women as controls." (PMID 31798591, 2019). "The extension of the study to a larger number of patients will better define the involvement of IL-31 in the pathogenesis of osteoporosis." (PMID 26449657, 2015). "Until now, involvement of the Th2 cytokine interleukin-31 (IL-31) in osteoporosis hadn’t yet been studied." (PMID 26449657, 2015). "In this study, we have demonstrated for the first time an increase of IL-31 serum levels in postmenopausal women with decreased bone mineral density, discovering that there seems to be a correlation between this cytokine and osteoporosis." (PMID 26449657, 2015). "The aim of our study was to evaluate the possible involvement of IL-31 also in subjects affected by osteoporosis." (PMID 26449657, 2015). "A variety of cytokines and transcription factors are reported to be involved in the development of osteoporosis, and some of them are regulated by IL-31." (PMID 26449657, 2015). "Studies in postmenopausal women revealed significantly elevated serum IL-31 levels (43.12 ± 6.97 pg/mL vs. 29.58 ± 6.09 pg/mL in healthy controls) and significantly reduced IL-33 levels (3.53 ± 2.45 pg/mL vs. 13.72 ± 5.39 pg/mL) in osteoporosis patients." (PMID 41368642, 2025). "In addition, the IL-33/IL-31 axis is known to play a significant role in the development of osteoporosis." (PMID 39767728, 2024). "IL-31 and IL-33 are two cytokines of the Th2 cytokine lineage which play a role in osteoporosis." (PMID 35707276, 2022). "Better knowledge of the role of IL-31 and IL-33 and their receptor complexes in osteoporosis could provide an interesting perspective for the development of new and more effective therapies, possibly with less side effects." (PMID 32069819, 2020). "The role of IL-33/ST2 axis in Th2/IL-31 and Th17 immune response characterizing the development of allergic respiratory pathologies has been clarified while the relationship between the two cytokines in osteoporosis is still controversial." (PMID 31973226, 2020). "Th2 cytokines do not always positively affect the bone, but they may even contribute to the development of osteoporosis, as we demonstrated in a recent study, in which the Th2 cytokine IL-31 was significantly involved in osteoporosis development." (PMID 32069819, 2020). "Our results suggest a key role of IL-31 in senile osteoporosis but the exact mechanism of action remains unknown." (PMID 31798591, 2019). "Moreover, our data clearly showed a relationship between IL-31 expression and osteoporosis in aging, as reflected by the higher levels of this cytokine in aged patients." (PMID 26449657, 2015). "Our results suggest that an important role is played by IL-31 in senile osteoporosis." (PMID 26449657, 2015). "Furthermore, Th2 cells can contribute to osteoporosis via the IL-33/IL-31 axis." (PMID 41368642, 2025). "In addition, higher levels of IL-31 were found in patients with more advanced age, suggesting an involvement of this cytokine in the processes driving immunosenescence and age-related diseases, particularly senile osteoporosis." (PMID 32069819, 2020). "Therefore, this study reveals the relationship between IL-31 expression and osteoporosis." (PMID 26449657, 2015). "Therefore, IL-31 may rather play a role unique to osteoporosis, which represent a chronic condition where Th1 inflammation plays a more dominant role." (PMID 26449657, 2015). "Recently, there was reported an involvement of the IL-33/ST2 axis in the generation of Th17 cells and the production of IL-31 and that the IL33/IL-31 axis is a link between osteoporosis and accelerated atherosclerosis in psoriatic arthritis." (PMID 31973226, 2020).
osteoporosis (continued). "Our results showed a statistically significant increase of IL-31 serum levels in postmenopausal women with decreased BMD, suggesting a role of IL-31 in osteoporosis." (PMID 31798591, 2019). "Moreover, IL-31 increase that we found in aged osteoporotic patients, probably related to the increased release of this cytokine by senescence inflammatory immune cells, might therefore contribute to the development of a condition of full-blown osteoporosis." (PMID 26449657, 2015). "The cytokines IL31 and IL33 are reported to play a role in bone remodeling and osteoporosis." (PMID 39767728, 2024). "Contrary to IL-31, IL-33 inhibits bone resorption by inhibiting osteoclastic genes, including RANKL, which may become one of the key points to treat osteoporosis." (PMID 35707276, 2022). "Increased levels of serum IL-31 are observed in postmenopausal women with a decrease of bone mineral density correlating with age, but not with the presence of fractures or osteoporosis degree." (PMID 31973226, 2020). "Serum IL-31 levels are not related with the severity of osteoporosis, as indicated by BMD values and/or the presence of fractures." (PMID 31798591, 2019). "Serum IL-31 levels did not reflect the severity of osteoporosis, as assessed by BMD values and/or the presence of fractures." (PMID 26449657, 2015). "The IL-31/IL-31RA interaction, through the mediation of STAT1/3/5 and MAPK activation, starts signals leading to pro-inflammatory cytokine and chemokine expression, that exert central roles in both Th2 cytokine-mediated inflammatory diseases and bone resorption, leading to osteoporosis." (PMID 32069819, 2020).
allergic contact dermatitis (9 papers, 2012 to 2022). An inflammatory skin condition caused by an immune response to direct contact between the skin and an allergen. "Regarding allergic-skin disorders, the role of IL-31 has also been studied in allergic-contact dermatitis (ACD) and chronic-spontaneous urticaria (CSU)." (PMID 35742951, 2022). "In addition, IL-31 mRNA expression was also increased in skin samples of patients with allergic contact dermatitis and was correlated with IL-4 and IL-13 levels." (PMID 22853438, 2012).
allergic rhinitis (9 papers, 2012 to 2023). Inflammation of the nasal mucous membranes caused by an IgE-mediated response to external allergens. "Very recent evidence showed pollen antigen-induced IL-31 protein production from PBMCs in patients with allergic rhinitis in association with the severity of allergic rhinitis." (PMID 22853438, 2012). "Okano and collegues reported that around two thirds of these PBMCs produced detectable amounts of IL-31 in response to pollen allergens in vitro in association with the severity of allergic rhinitis." (PMID 22853438, 2012). "Interleukine-31 (IL-31) is involved in allergic rhinitis and skin-based autoimmune disorders such as pruritis, alopecia, psoriasis, and atopic dermatitis." (PMID 36979525, 2023). "The first indication for a role of IL-31 in allergic rhinitis was provided by the characterization of in vitro IL-31 production in pollen antigen–induced PBMC responses in patients with allergic rhinitis." (PMID 22853438, 2012). "In the present study we studied the release of IL-31 and IL-13 in allergen-challenged allergic rhinitis patients." (PMID 22853438, 2012). "We observed nasal IL-31 at detectable levels in five of seven allergic rhinitis patients, four of these peaked at 5 h after nasal provocation." (PMID 22853438, 2012). "We demonstrated the release of IL-31 into ipsilateral nasal secretions after unilateral nasal allergen challenge in patients with allergic rhinitis." (PMID 22853438, 2012). "In which way IL-31 modulates the inflammatory reaction and type 2 responses in allergic rhinitis remains to be investigated." (PMID 22853438, 2012). "If IL-31 is an interesting candidate for therapeutical interventions in allergic rhinitis remains to be elucidated." (PMID 22853438, 2012). "To further elucidate the potential role of IL-31 in allergic rhinitis, we studied the release of IL-31 and IL-13 into nasal secretions and serum after unilateral allergen challenge in seasonal allergic volunteers." (PMID 22853438, 2012). "Our study demonstrates for the first time that IL-31 is released into nasal secretions after nasal pollen allergen challenge in patients with allergic rhinitis." (PMID 22853438, 2012). "The observed local upregulation of IL-31 mainly during the late phase reaction after nasal allergen challenge suggests a role of IL-31 in allergic rhinitis." (PMID 22853438, 2012). "Indeed, compared to healthy controls, patients with asthma or allergic rhinitis showed higher serum IL‐31 concentrations, which correlated positively with Th2‐related cytokines and disease severity." (PMID 32648940, 2021). "Additionally, functional assays to explore the roles of IL-31 on the cellular influx and its effects on resident cells in allergic rhinitis should be considered." (PMID 22853438, 2012). "Furthermore, allergen-induced IL-31 protein production by PBMCs in patients with allergic rhinitis was significantly and positively correlated with the production of IL-13." (PMID 22853438, 2012). "We found a correlation trend of IL-31 contents with the severity of allergic rhinitis." (PMID 22853438, 2012). "Furthermore, we also found IL-31 contents to show correlation trends to symptoms and thus the severity of allergic rhinitis, suggesting that IL-31 production might lead to a deterioration in the pathophysiology of allergic rhinitis." (PMID 22853438, 2012). "It has been reported that an increase in IL-31 levels was detected in patients with allergic rhinitis and IL-31 induced production of IL-4, IL-5 and IL-13 in PBMC and nasal epithelial cells from patients with allergic rhinitis." (PMID 30647024, 2019).
bullous pemphigoid (9 papers, 2017 to 2025). Bullous pemphigoid (BP) is the most common form of autoimmune bullous dermatosis. "A number of studies demonstrated the expression of IL-31 and its receptor in this condition and bullous pemphigoid appears to be a very interesting candidate for clinical studies targeting IL-31 signaling." (PMID 33644104, 2021). "The autoimmune blistering skin disease, bullous pemphigoid (BP), is accompanied by severe pruritus, thus suggesting possible involvement of IL-31." (PMID 31281316, 2019). "The aim of this paper was to evaluate role of IL-31 in development of itch in a course of bullous pemphigoid and dermatitis herpetiformis." (PMID 28808661, 2017). "IL-31 has been reported to promote helper Th2 cell-driven inflammation and stimulate eosinophil activation, suggesting a potential link between IL-31 and bullous pemphigoid, which has Th2-driven inflammation and eosinophil infiltration as a pathologic mechanism." (PMID 41169429, 2025). "Maybe in a course of bullous pemphigoid and dermatitis herpetiformis there is deposition of IL-31 in changed areas." (PMID 28808661, 2017). "The primary goal of this research is to assess the relationship between serum levels of IL-31, IL-5, and SII and disease status among patients with bullous pemphigoid (BP)." (PMID 41169429, 2025).
chronic spontaneous urticaria (9 papers, 2013 to 2023). "Interestingly, it was reported that inhibition of OSMR results in suppressed IL-31, which was highly expressed in the skin of patients with chronic spontaneous urticaria and was released from isolated basophils accompanied with anti-IgE activation." (PMID 30134804, 2018). "Regarding basophils, IL-31 has been shown in chronic spontaneous urticaria and healthy donors, and no study using AD-derived basophils has shown IL-31 production." (PMID 36993985, 2023).
inflammatory bowel disease (9 papers, 2015 to 2025). A spectrum of small and large bowel inflammatory diseases of unknown etiology. "Contrary to our results, it appears that inflammatory bowel disease may negatively influence the levels of IL-31 in the gingival tissues." (PMID 37958576, 2023).
lung fibrosis (8 papers, 2021 to 2024). "Our findings suggest a pathogenic role for IL-31/IL-31RA signaling during bleomycin-induced pulmonary fibrosis." (PMID 33815402, 2021). "Of note, serum IL-31 levels positively correlated with the severity of skin and lung fibrosis and serum levels of IL-4, IL-6, and IL-13, which suggests the association of IL-31 with fibrosis and Th2 immune responses in SSc." (PMID 34642338, 2021). "Therefore, we studied the effect of IL-31 on airway epithelial cells in the production of pro-fibrotic cytokines associated with pulmonary fibrosis." (PMID 33815402, 2021). "Notably, the loss of IL-31 signaling attenuated collagen deposition and lung function decline during bleomycin-induced pulmonary fibrosis." (PMID 33815402, 2021). "The expression of IL-31 is elevated in human IPF lungs, and blockade of IL-31 signaling inhibits collagen deposition, attenuates the decline in lung function, and improves pulmonary fibrosis." (PMID 36825939, 2023). "IL-31 promoted skin and lung fibrosis and enhanced Th2 immune responses, which were ameliorated by the blockade of IL-31 or anti-IL-31RA antibody." (PMID 35185577, 2022). "In fibrotic diseases, several of IL-6 family cytokines including IL6 and OSM have been shown to induce pulmonary fibrosis, but the contribution of IL-31/IL-31RA signaling in lung fibrosis has remained unexplored." (PMID 33815402, 2021). "Here, we dissected the pro-fibrotic role of the IL-31/IL-31RA axis using a mouse model of bleomycin-induced pulmonary fibrosis." (PMID 33815402, 2021). "Together, these studies indicate that IL-31-driven signaling is a key factor driving pulmonary fibrosis." (PMID 33815402, 2021). "The current study aimed to determine the role of IL-31/IL-31RA signaling in the pathogenesis of pulmonary fibrosis using a bleomycin-induced lung fibrosis model and IL-31RA deficient mice." (PMID 33815402, 2021). "SSc patients with elevated serum IL-31 levels had higher frequencies of dcSSc, pulmonary fibrosis, and esophagus involvement, all of which are the clinical consequences of fibrosis, when compared to the patients with normal IL-31 levels." (PMID 34642338, 2021). "A profibrotic function of IL-31 has also been reported, and it may contribute to skin and lung fibrosis in a subset of patients with SSC." (PMID 36136606, 2022). "We applied the whole lung transcriptome through RNA seq analysis to identify IL-31/IL-31RA -dependent genes and pathways that might participate in IL-31-driven pulmonary fibrosis." (PMID 33815402, 2021). "In addition, whole lung transcriptome analysis revealed a decrease in the expression of ECM-related genes, which thus supports the role of IL-31/IL-31RA in lung fibrosis." (PMID 33815402, 2021). "However, the role of IL-31/IL-31RA signaling in pulmonary fibrosis has remained unexplored." (PMID 33815402, 2021). "Thus, therapeutic targeting the IL-31-IL-31RA axis may prevent collagen deposition, improve lung function, and have therapeutic potential in pulmonary fibrosis." (PMID 33815402, 2021). "While IL-31 has been identified in several inflammatory and remodeling diseases, mechanistic studies evaluating IL-31 producing cells in IPF, and the role of IL-31 in pulmonary fibrosis have been missing." (PMID 33815402, 2021). "Indeed, stimulation of airway epithelial cells with IL-31 induced an increased production of MCP1 and IL-6 cytokines known to play a role in the development of pulmonary fibrosis." (PMID 33815402, 2021). "However, additional studies are needed to identify specific mechanisms by which IL-31 contributes to ECM production and decline in lung function during bleomycin-induced pulmonary fibrosis." (PMID 33815402, 2021). "However, the role of IL-31/IL-31RA signaling in the pathogenesis of pulmonary fibrosis has not been definitively determined." (PMID 33815402, 2021).